NDE1 (nudE neurodevelopment protein 1)
Diseases named in the same sentence as NDE1 in open-access papers (continued):
Sharing a sentence is not in itself a finding about the gene and the disease.
tumor (5 papers, 2012 to 2024). "In summary, it can be seen that NDE1 has a significantly increased level of expression in a majority of tumours, and its association with the clinical stage of many malignancies has been established by us." (PMID 38466053, 2024). "In summary, increased NDE1 expression is linked to a poor prognosis in the majority of tumours." (PMID 38466053, 2024). "The GEPIA2 portal examined the association between NDE1 expression and tumour grade." (PMID 38466053, 2024). "Numerous tumour types have elevated NDE1, which is linked to a bad prognosis." (PMID 38466053, 2024). "Our research revealed that NDE1 is strongly linked to tumour mutation burden (TMB), microsatellite instability (MSI), tumour purity and homologous recombination deficit (HRD) in a range of tumours, in addition to immune checkpoint genes in the majority of tumours." (PMID 38466053, 2024). "Hence, it was postulated that NDE1 could be implicated in the pathogenesis and advancement of tumours." (PMID 38466053, 2024). "While NDE1 expression was inversely connected with tumour grade in ESCA and OV, it was favourably correlated with tumour stage in ACC, KICH, LIHC and PAAD." (PMID 38466053, 2024). "It was discovered that the expression level of NDE1 mRNA in healthy human subjects was low (NX < 50) after using the Human Protein Atlas to examine the normalised expression level of NDE1 in different tumour tissues and paracancerous tissues." (PMID 38466053, 2024). "The findings demonstrated a correlation between the degree of NDE1 expression and the immunological subtypes of 30 tumours and the molecular subtypes of 17 tumours." (PMID 38466053, 2024). "In this work, we first examined the amount of NDE1 expression in different malignancies and discovered that NDE1 expression was considerably greater in a number of tumours than in normal tissues." (PMID 38466053, 2024). "The additional graphic illustrates how NDE1 and other tumours' immunological and molecular subtypes are related to one another." (PMID 38466053, 2024). "According to the median of NDE1 expression, the tumour samples were divided into high‐ and low‐expression groups using the GEPIA2 database." (PMID 38466053, 2024). "We conducted a study using the TISMO database to determine whether the expression level of NDE1 has an effect on tumour immunotherapy." (PMID 38466053, 2024). "In 15 tumours, a strong correlation between NDE1 and tumour purity was discovered." (PMID 38466053, 2024). "Additionally, we visualised the connection between immune infiltration and NDE1 in different tumours in the TIMER2 database using scatter plots." (PMID 38466053, 2024). "Additionally, when the progression‐free interval and NDE1 expression were examined, it was shown that the high levels of NDE1 expression in eight different tumour types (GBMLGG, LGG, LIHC, BLCA, MESO, PAAD, ACC and KICH) were associated with a poor prognosis." (PMID 38466053, 2024). "In light of the association between immune infiltration, MSI, TMB, tumour purity and NDE1 expression level that we previously examined, we hypothesise that NDE1 may have some bearing on the sensitivity to tumour immunotherapy." (PMID 38466053, 2024). "As a result, NDE1 may influence the epigenetic state of tumours to control tumour immunity." (PMID 38466053, 2024). "Therefore, we make the assumption that NDE1 could function as an oncogene, promoting the development and spread of a range of tumours." (PMID 38466053, 2024). "We used the TMB function in the R package maftools (version 2.8.05) to determine the tumour's total metabolic burden (TMB), and we then looked at the relationship between TMB and NDE1 expression level." (PMID 38466053, 2024). "However, there are few or even nonexistent studies on the relationship between NDE1 and tumours." (PMID 38466053, 2024).
neurodegenerative disease (1 paper, 2017). A disorder of the central nervous system characterized by gradual and progressive loss of neural tissue and neurologic function. "Given the central role of mitochondria in cellular energy metabolism and the fact that glycolytic metabolic networks are often dysregulated in neurodegenerative diseases, we decided to focus on two main energy metabolism-associated interaction partners, Pfk26 and Nde1." (PMID 29234670, 2017).
NDE1 also shares sentences with these, for which no sentence is quoted: brain disease (3 papers); microhydranencephaly (3); attention deficit-hyperactivity disorder (2); cognitive deficits (2); infection (2); Baraitser-Winter syndrome (1); bipolar disorder (1); brain tumor (1); ciliopathies (1); developmental delay (1); hydrocephaly (1); Joubert syndrome (1); lymphoma (1); neurological disorders (1); Pachygyria (1); Proteus syndrome (1); psychosis (1); pulmonary hypertension (1); sleep disorder (1).